IL2 (interleukin 2)
Diseases named in the same sentence as IL2 in open-access papers (continued):
Sharing a sentence is not in itself a finding about the gene and the disease.
tumor (continued). "In addition, the increased IL-2 and decreased IL-10 levels following SIT treatment suggest that SIT can also achieve anti-tumor effects by increasing the production of anti-tumor cytokines and reducing the release of immunosuppressive factors in the body." (PMID 35756648, 2022). "In this regard, TRM lymphocytes have been reported to express molecules involved in cytotoxic activities, such as granzyme B, perforin, IL-2 and IFN-γ, as well as exhaustion markers such as PD-1 and CTLA-4, likely representing tumor-specific effector cells induced by virus antigens." (PMID 36123711, 2022). "Tumor cells release EV PD-L1, which can interact with PD-1 on the surface of T cells, thereby inhibiting their effector function and reducing the release of the pro-inflammatory cytokines IFN-γ, IL-2, and granzyme-b." (PMID 35090497, 2022). "Moreover, the B2 CAR T-cells elaborated greater IL-2, IFN-γ, and TNF-α compared to B1 during long-term exposure to tumor cells." (PMID 35222421, 2022). "Moreover, Artemisia argyi polysaccharides (FAAP-02) were reported to improve anti-tumor activity by promoting the production of lymphocyte, TNF-α, IL-2, IL-4, IL-6, and IL-12." (PMID 35295918, 2022). "In addition, VEGF 44, ICAM-1 45-47, TGF-β 48, IL-2, IL-649-51, and TNF-α 52 play an important role in the growth and metastasis of tumor cells, and can affect the expression of co-inhibitory molecules on immune cells." (PMID 36118529, 2022). "Signal in BDCA-2 CAR T cell and BDCA-2 CAR T cell + IL-2 treated animals increased continuously from day 0 on without a strong signal decline at the beginning, nor resulting in any anti-tumor effect." (PMID 35836798, 2022). "Boosting of IL-2 serum concentration did not enhance the abscopal effect of combined tumor treatment using calcium electroporation and bleomycin electrotransfer; however, it had a significant inhibitory effect on directly treated tumors." (PMID 35954434, 2022). "Furthermore, the antibody–cytokine fusion protein Daromun is a combined molecule consisting of IL-2 and TNF fused to the monoclonal antibody L19, which is specific to the alternatively spliced extra-domain B of fibronectin, a marker of tumor angiogenesis." (PMID 35158808, 2022). "Strikingly, pCAR T-cells produced significantly more IL-2 over early tumor re-stimulation cycles, unlike CAR T-cells in which specificity was conferred by the same mutated scFv or F-2." (PMID 35222427, 2022). "Remarkably, NKp44/PDGF-DD interaction promotes the secretion of IFN-γ and TNF-α by IL-2-activated NK cells, but not cytotoxicity, limiting tumor cell growth in vitro and tumor spread in a transgenic NCR2 mouse model." (PMID 35757695, 2022). "In this study, we showed that N. caninum injection increased infiltration of CD8+ T cells and macrophages into the tumor, along with increased expression of IL-12, IFN-γ, IL-10, TNF-α, and IL-2 mRNA, which can also be induced by N. caninum in a mouse model, as reported in other studies." (PMID 36138417, 2022). "Although it is difficult to parse out the relative contribution of these Tregs vs conventional T cells as IL-2 consumers, it is not uncommon to observe the presence of large numbers of tumor infiltrating but non tumor-reactive T cells." (PMID 36520915, 2022). "Although Salmonella and Alb-IL2 monotherapies resulted in partial tumor control, we think that the lack of T cells entering the TME was a contributing factor to the eventual tumor outgrowth." (PMID 35962391, 2022). "Although this did not enhance the abscopal effect of combined tumor treatment using calcium electroporation and bleomycin electrotransfer, boosting of IL-2 serum concentration had a significant inhibitory effect on directly treated tumors." (PMID 35954434, 2022). "CD4+ Tconv cells produced more IFN-γ in the tumor compared with matched peripheral blood independent of pretreatment but showed enhanced IL-2 production in the NEO cohort compared with the PR cohort." (PMID 36509285, 2022).
tumor (continued). "Moreover, neoadjuvant chemotherapy increased the production of proinflammatory cytokines by tumor-infiltrating T cells, with enhanced TNF-α and IL-2 and reduced IL-4 and IL-10 expression." (PMID 36509285, 2022). "The exhausted tumour-specific T-cells do not express characteristic pro-inflammatory cytokines such as IL-2, TNFα, and IFNγ, but instead produce the inhibitory receptors such as programmed death 1 (PD-1) and cytotoxic T-lymphocyte associated protein 4 (CTLA4)." (PMID 36140243, 2022). "Aside from the IL-2, IFN-α induces tumor regression in about 15% of patients with RCC." (PMID 36510217, 2022). "We further hypothesized that DMXAA could render the tumor microenvironment more permissive and responsive to biological molecules such as agonist anti-CD40 antibody or IL-2 to further enhance the immune response." (PMID 36466911, 2022). "IFN‐γ could promote T cells differentiate to tumor‐specific CD4+ T cells and expansion of CTLs, while IL‐2 promoted activation and proliferation of NK cells." (PMID 35652198, 2022). "The selected anti-PD-1 scFv could restore the production of IL-2 and IFN-γ by Jurkat T cells that were co-cultured with PD-L1 positive tumor cells." (PMID 35996120, 2022). "Additional IL-2 supply resulted in a higher frequency of CD3-positive cells within the outer 300 μm of the tumor margin, independent of the target specificity." (PMID 35836798, 2022). "Given that cDC1 plays an important role in tumor-specific T cell activation, these features may affect Pmel-1 activity in TBI/IL-2-treated mice." (PMID 36497152, 2022). "We have shown that three i.t. injections of IL-2 modified tumor blood vessels and recruited CD8+ T cells into the tumor bed whilst three i.t. injections of IL-2 combined with an agonist anti-CD40 antibody recruited a massive and simultaneous infiltrate of neutrophils and T cells." (PMID 36466911, 2022). "IL15 has been a primary cytokine of interest in immunotherapy due to its ability to activate the main anti‐tumour cell effectors, but does not, in contrast to IL2, stimulate immune‐suppressing regulatory T cells (Treg)." (PMID 35758207, 2022). "A synthetic IL-2 circuit T cell without co-delivery of a tumor reactive cytotoxic T cell population did not produce tumor control in these NSG mouse models." (PMID 36520915, 2022). "This almost eliminated mis-pairing between the introduced EBV-Sc-TCR and endogenous TCR chains, and we further enhanced tumor-specific TCR expression, functional avidity, and IL-2 production by introducing an extra intra-chain disulfide bond between the Vα and the poly-linker." (PMID 35432319, 2022). "T cells express IL-2 and IFN-γ receptors stimulated by the corresponding cytokines produced by CD4+ Th1 cells to activate CD8+ cytotoxic T cells and have a killing effect on tumor cells." (PMID 36012134, 2022). "We isolated CD8+ and CD8+PD-1+ T cells from patient PBMCs; expanded them in vitro for 15 days with IL-2, anti-CD3 stimulation, and irradiated feeders; and tested their ability to recognize autologous tumor cell lines by IFN-γ-ELISPOT using HLA-A2+ tumor cell lines as target cells." (PMID 35480107, 2022). "WAP can enhance phagocytosis by macrophages, while ALP enhances the activation of lymphocytes to increase the release of cytokines such as interleukin -2 (IL-2), interleukin -12 (IL-12), interferon-gamma (IFN-γ) and TNF-α, which together induce the necrosis and apoptosis of tumor cells." (PMID 36278230, 2022). "It increased dendritic cells (DC)s and CD4+ and CD8+ T cells, decreased B cells, induced the secretion of Th1 cytokines and IL-2, increased IFN-γ levels, and promoted DC maturation (CD86+ MHCII; higher levels of IL-12p40 and IL-12p70 were recorded, as was the inhibition of tumor growth." (PMID 33435246, 2021). "However, once the tumor process has already begun, TGF-β creates an immunosuppressive microenvironment by inhibiting IL-2, IL-12, and IFN-γ." (PMID 34518597, 2021).
tumor (continued). "Even though the anti-tumor efficacy of intratumoral IL-2 appears to be durable, it is limited to the injected lesions suggesting that intratumoral IL-2 does not have strong systemic effects." (PMID 33925915, 2021). "We observed the expression of IL-2 and TNF-a in the tumor samples, demonstrating virus replication." (PMID 32920593, 2021). "When incubated with mesothelin-positive tumor cells, Msln-CCR2b-CAR and Msln-CCR4-CAR T cell specifically exerted potent cytotoxicity and produced high levels of proinflammatory cytokines, including IL-2, IFN-γ, and TNF-α." (PMID 33777013, 2021). "Meanwhile, the high expression phenotype of miR-3614-5p enhanced NK T cell activation, negative T cell selection, response to interleukin 2, and response to tumor cells." (PMID 34127929, 2021). "In the tumor microenvironment, PD-1 expression is sustained highly on exhausted T cells, followed by the diminished production of effector factors, including interferon-gamma (IFN-γ), interleukin-2 (IL-2), and tumor necrosis factor-alpha (TNF-α)." (PMID 34819055, 2021). "IL-2 is of particular interest as a potent cytokine capable of inducing the proliferation and differentiation of CD8 effector T cells (Teff), as well as other T, B, and NK lineages with anti-tumor potential." (PMID 34584159, 2021). "The fact that UA ATC exhibit non-MHC restricted cytotoxicity against tumor cells indicate that variable levels of IL-2 and IFN-γ are likely to be produced for their proliferation and anti-tumor activity." (PMID 34290709, 2021). "Upon overproduction, IL-10 may impair the immune response by inhibiting the production of IL-2, IFN-γ, and IL-12, which are essential for virus and tumor cell clearance." (PMID 33750983, 2021). "We observed significant negative correlations between CD68+ macrophage infiltrations in the tumor tissue and the concentrations of the cytokines eotaxin, IFN-γ, IL-1β, IL-2, IL-10, IL-13, IL-16, VEGF and factor score of component 2 (“Inflammatory Cluster”) in the CSF." (PMID 34654395, 2021). "It must be noted that MDSCs derived from non-tumor bearing MUC1KO but not WT mice induced suppression of IL2 and IFN-γ production by T cells." (PMID 34070449, 2021). "In addition, the action of histamine is synergistic with IL-2 and IFN-α, leading to the killing of a large number of NK cell-sensitive human tumor cells in vitro and in vivo." (PMID 34439898, 2021). "MHCI in tumor cells is recognized by the CD8 molecule to help stimulate CD8+ T cells; we speculated that this increases IL2 expression in the A549 co-cultured CD8+ T cells." (PMID 34680466, 2021). "In addition, Tien-Hsien liquid (THL) accelerated the secretion of immune factors including IFN-γ, IL-2 and TNF-α to augment the cytotoxicity of NK cells and CTLs and mitigate the tumor development." (PMID 34722304, 2021). "In the 1990s, cytokines such as interferon-α (IFN-α) and interleukin-2 (IL-2) that non-specifically activate the anti-tumor immune response began to be used to treat metastatic ccRCC." (PMID 33746989, 2021). "The first is the treatment of dogs with appendicular osteosarcoma consisting of in vitro tumor cell expansion, intradermal tumor cell injections, mononuclear cell collection and in vitro expansion, and infusion of expanded CD3+ T-cells followed by serial IL-2 injections." (PMID 34950726, 2021). "Moreover, when compared to the control group, anti-HPV16-L1, IL-2 and IFN-γ in serum and HPV16-L1 protein in tumor tissues was robustly increased in the HPV16-L1 and combination groups." (PMID 34635698, 2021). "However, anti-TIGIT/anti-PD-1 co-blockade increased IFN-γ, TNF-α and IL-2 in CD8+ TILs and resulted in complete tumor regression in all mice." (PMID 34367161, 2021). "IL-2 activation of the IL-2 Rβγ complex induces proliferative and activation signals through STAT5 phosphorylation that drive effector T and natural killer (NK) cell expansion and tumor clearance." (PMID 34373459, 2021).
tumor (continued). "In addition, lnc-Tim3 was found to be upregulated in tumor-infiltrating CD8 T cells of HCC patients, and negatively correlated with IFN-γ and IL-2 production." (PMID 34830805, 2021). "The efficient tumor cell lysis induced by these mAbs was explained by the increased activation of lymphocytes co-cultured with tumor cells, leading to enhanced levels of IFN-γ and IL-2 release, with respect to those treated with atezolizumab and ipilimumab." (PMID 35008285, 2021). "The cytolytic activity of TCR-TMART-1 was inhibited by increasing the percentage of tumor cells expressing PD-L1, affecting the secretion of Granzymes and pro-inflammatory cytokines in Tnull and TCR-TMART-1, including TNFα, IFNγ, and IL2." (PMID 33754038, 2021). "Researches have shown that miR155 upregulation promotes the differentiation of naive CD4+ T cells into Th1 cells through the regulation of the IFN-γ signal, which is of great significance for T cells to exert anti-tumor function for the secretion of IFN-γ, TNF-α, IL-2 and other cytokines." (PMID 35046962, 2021). "The next generation of IL-2 that specifically targets tumor and preferentially boosts CD8+ T-cell response without inducing Treg responses appears to be promising." (PMID 34394124, 2021). "2x105 purified peritoneal CD8+ T cells from PBS, vvDD or vvDD-IL15/Rα treated mice were given IP in conjunction with stimulatory doses of human IL-2 (50,000 IU) to 7-day peritoneal MC38-luc tumor-bearing mice after a preparatory regimen of sublethal whole-body irradiation (5Gy)." (PMID 33679747, 2021). "There are also studies that combine IL-2 and CXCL9 to slow angiogenesis and tumor progression." (PMID 33854600, 2021). "Our data revealed that IL-2 and STAT1 was enriched in tumor cells." (PMID 34026600, 2021). "Tumor-bearing mice received CTX, activated pmel-1 Thy1.1+CD8+ T cells, and IL-2 and/or IL7-Fc." (PMID 34440787, 2021). "CDX-527 was demonstrated to have potent T-cell activation by increasing IL-2 and IFNγ production and anti-tumor activity to CD27-expressing lymphoma cells in an immunodeficient mouse model, with comparable anti-tumor activity to separate CD27 agonizing and PDL1 inhibiting monoclonal antibodies." (PMID 34630390, 2021). "Morris analysis was performed by considering the population of tumor cells, NK cells, CTLs, MDSCs, T helper, Tregs, and cytokines IL-2, IFN-γ, and TGF-β (in no treatment case) at day 100 of simulation as a read-out." (PMID 34781899, 2021). "The authors co-delivered interleukin-2 as a T-cell growth factor and all-trans retinoic acid (ATRA), which can induce differentiation of MDSCs to mature DCs, macrophages, and granulocytes, using dHMLB (A/D/I-dHMLB) into the tumor-bearing mouse model." (PMID 34576180, 2021). "In contrast, TRM-like cells found in endometrial and breast cancer retained equal capacities to produce IFN-γ, TNF-α and IL-2, compared with tumor-infiltrating T cells that did not display a TRM phenotype." (PMID 34571883, 2021). "However, some studies have found that increasing the serum levels of IL-2, IL-6, IL-12, and TNF-α in tumour-bearing mice regulates the growth and differentiation of lymphocytes and activate macrophages, playing a regulatory role in antitumour immunity." (PMID 34801005, 2021). "This experiment evaluated the effects of combination therapy and single therapy based on cytokine secretion using ELISA to quantify IFN-γ, TNF-α, IL-2, and IL-10 which is a negative immunoregulatory factor, in tumor tissues." (PMID 33792840, 2021). "TALL-104 is well-known for its MHC non-restricted tumoricidal activity even after IL-2 deprivation and it has the ability to discriminate between tumor and normal cells." (PMID 34676046, 2021). "Consistent with previous studies, concomitant analyses of immune activation cytokines indicated that nivolumab treatment also significantly increased the production of IFN-γ, IL-2, and TNF-α, of which IFN-γ has been a key cytokine in IL-10 mediated anti-tumor responses." (PMID 34769278, 2021).
tumor (continued). "Indoleamine 2,3-dioxygenase (IDO) promotes the production of the immunosuppressive tryptophan catabolite, L-kynurenine, which interferes with the IL-2-induced upregulation of NKp46 and NKG2D expression, thereby reducing the ability of NK cells to recognize and kill tumor cells." (PMID 34177887, 2021). "Of the cells isolated from MC38 tumors, the bystander memory cells showed superior cytokine production to the tumor-specific T cells and contained on average 3.7-fold more IFN-γ+ TNFα+ cells, and nearly 9-fold more IFN-γ+ IL-2+ cells than tumor-specific T cells." (PMID 34867942, 2021). "Similar to conventional CAR-T, 7×2b CAR-T cells could also inhibit tumor growth and increase IFN-γ, Gzms-B, and IL-2 expression." (PMID 34778046, 2021). "In addition, higher IL2, IFN-γ, and TNF families (e.g. CD40) represents a favorable cellular immunity and anti-tumor ability of C3." (PMID 33637086, 2021). "In tumor-bearing mice, APS could also boost T lymphocytes proliferation and enhance the release of IL-2 and IFN-γ in the peripheral circulation." (PMID 34721026, 2021). "This suggests that HD IL-2 efficacy may have been limited by the simultaneous promotion of anti-tumor CD8+ T cell and tumor-protective regulatory T cell proliferation." (PMID 34777395, 2021). "TIL preparation involves tumor excision, digestion, culture with IL-2, and assessment for specific tumor recognition; tumor-specific TIL cultures are then expanded using anti-CD3 monoclonal antibody, high IL-2 concentrations, and irradiated allogeneic feeder cells." (PMID 34881261, 2021). "The costimulatory molecule, CD28, induced and increased production of IL-2, enhancing the clonal expansion and endurance of CAR T cells that, when combined with 4-1BB/CD137, were more efficient in INF-γ production and lysis of tumor cells." (PMID 35011678, 2021). "Furthermore, the ROR1 CAR-T cells were able to promote significant IL-2 and IFN-γ production and successfully penetrated and proliferated within the 3D tumor model." (PMID 33670942, 2021). "In the tested time frame, tumor cytotoxicity (red curve) was the most sensitive readout for cibisatamab, with an EC50 38-fold lower than T-cell activation and approximately 145- and 96-fold lower than IL2 and IL6 release, respectively." (PMID 34862519, 2021). "Engineered NDV vectors expressing apoptin, immune checkpoint blockades like anti-CTLA-4, anti-PD-1, anti-PDL, and cytokines like IL-2 and influenza virus NS1 trigger oncolytic cell death in tumor cell lines from lung and liver, tumor-bearing mice, and apoptosis-resistant cells, respectively." (PMID 34063663, 2021). "NK-92/5.28.z cells secreted high amounts of effector molecules such as granzymes, granulysin, and perforin upon interaction with RMS tumor cells, while the levels of secreted cytokines such as TNF-α, IL-2, IL-6, and IL-4 were minimal or below the detection limit." (PMID 33809981, 2021). "IL-2, approved by the Food and Drug Administration (FDA) for metastatic kidney cancer and for metastatic melanoma acts by stimulating the proliferation of T cells, cytotoxic T lymphocytes (CTL) specific to tumours, NK cells and possibly intratumor lymphocytes." (PMID 33650838, 2021). "MUC16ecto- BiTEDs cocultured with T-cells in the absence of tumor cells did not display increased granzyme B, IL-2 or IFN-γ." (PMID 33936101, 2021). "In addition, hIL15-ABD can also promote the activity of IL-2 and IFN-γ in CD8+ T cells or NK cells, supporting more effective anti-tumor activity by effector cells." (PMID 33918641, 2021). "However, they used IL-2/OKT-3-expanded lymphocytes from patients and analyzed proliferation as well as the recognition of tumor cell lines by virally TCR-transduced T cells." (PMID 34769379, 2021). "Additionally, in the 99mTc-IL2 scan, the target-to-background ratio significantly correlated with the number of IL2R-positive tumor-infiltrating lymphocytes." (PMID 34445532, 2021).